METTL3 (methyltransferase 3, N6-adenosine-methyltransferase complex catalytic subunit)
Diseases named in the same sentence as METTL3 in open-access papers (continued):
Sharing a sentence is not in itself a finding about the gene and the disease.
heart failure (21 papers, 2019 to 2026). Inability of the heart to pump blood at an adequate rate to meet tissue metabolic requirements. "The overexpression of METTL3 was shown to cause spontaneous hypertrophy, whereas METTL3 knockdown leads to maladaptive remodeling and signs of heart failure." (PMID 31881725, 2019). "Studies to date have shown that METTL14 can be preferentially reduced, relative to METTL3, in a variety of cellular contexts and have profound effects on cell development, cancer, and late-stage heart failure." (PMID 40266881, 2025). "In the present study, we for the first time identified levosimendan, an approved anti- heart failure drug, as a new Mettl3 inhibitor, which supported by the dot blot assay and methyltransferase activity examination." (PMID 40765834, 2025). "The target transcriptions of METTL3 or FTO determine their roles of in the progression of heart failure." (PMID 35836571, 2022). "m6A content has been reported to be increased in human heart failure samples, and increased expression of the m6A RNA methylase METTL3 was sufficient to promote cardiomyocyte hypertrophy both in vitro and in vivo." (PMID 34266473, 2021). "The inhibition of METTL3 in mice hearts can lead to heart failure, whereas the overexpression of METTL3 promotes the development of hypertrophy in cardiomyocytes, highlighting the critical importance of m6A RNA methylation in the heart for maintaining normal cardiac function." (PMID 35953789, 2022). "Additionally, Mettl3 was reported to modulate cardiac homeostasis through m6A modifications, and Mettl3 knockdown in cardiomyocytes promoted the progression of heart failure." (PMID 34413770, 2021). "Therefore, in the future, the research on FTO and METTL3 related myocardial ischemia and hypoxia may find a breakthrough for the therapeutic target of heart failure." (PMID 35811741, 2022). "This was also similar to another previous study in which the expression of METTL3 was higher in clinical failing heart samples from patients with left ventricular hypertrophy than in samples from healthy subjects without heart failure." (PMID 35836108, 2022). "METTL3 and FTO were proved to be the key regulators of m6A methylation in failure heart." (PMID 35836571, 2022). "This may be explained by the fact that METTL3 and FTO participate in the progression of heart failure by regulating m6A methylation of target transcriptions rather regulating than the global level of m6A methylation." (PMID 35836571, 2022). "Increased METTL3 expression regulates mitogen-activated protein kinase (MAPK) and intracellular signaling pathways and further mediates CM hypertrophy, whereas silencing of METTL3 prevents the ability of CM to hypertrophy In heart failure (HF), m6A methylation and METTL3 expression are elevated." (PMID 41194259, 2025).
myocardial infarction (20 papers, 2021 to 2026). Gross necrosis of the myocardium, as a result of interruption of the blood supply to the area, as in coronary thrombosis. "METTL3 deficiency also contributed to heart regeneration after myocardial infarction via facilitating cardiomyocytes to re‐enter the cell cycle." (PMID 36564367, 2023). "Previous studies have demonstrated the functional importance of cardiac Fat mass and obesity-associated protein (FTO)-dependent m6A methylome during myocardial infarction and cardiac growth control by Methyltransferase Like 3 (METTL3)." (PMID 34124185, 2021). "Combined with the results showing that m6A methylation was increased in CFs treated with hypoxia and in cardiac fibrotic tissue post‐MI, we finally chose to study the role of METTL3 in the process of myocardial fibrosis after myocardial infarction." (PMID 40913254, 2025). "In a recent study, silencing METTL3 reduced m6A modification levels in fibrosis-related genes and decreased myocardial fibrosis in mice with myocardial infarction." (PMID 40005339, 2025). "Our results demonstrated that ATG7 knockdown reversed the elevated autophagy levels observed in the hearts of METTL3-CKO mice following myocardial infarction." (PMID 39893158, 2025). "Here, we investigated the impact of METTL3, a key m6A methyltransferase, on the autophagy regulation in ischemic and hypoxic cardiomyocytes, as well as in mice following acute myocardial infarction (AMI)." (PMID 39893158, 2025). "After treatment with a hypoxic solution and exposure to a 1% O2 hypoxic environment to simulate myocardial infarction, Western blot analysis revealed that the levels of METTL3 and autophagy initially increased and then decreased with prolonged hypoxia time." (PMID 39893158, 2025). "Myocardial infarction affects the expression of METTL3, and METTL3 also regulates the apoptosis of cardiomyocytes during myocardial infarction." (PMID 36980863, 2023). "During in vivo experiments, we confirmed that overexpression of METTL3 promoted the deterioration of cardiac function after myocardial infarction in mice." (PMID 36980863, 2023). "In the present study, we report that METTL3, an important RNA methylation enzyme, participates in the methylation process of myocardial infarction." (PMID 36980863, 2023). "Myocardial infarct size and cardiac function were also analysed to determine the consequent effects of METTL3." (PMID 35040253, 2022). "METTL3 was significantly upregulated in mouse model of myocardial infarction (MI) and TGF-β1-treated cardiac fibroblasts (CFs)." (PMID 36093141, 2022). "In myocardial infarction models, METTL3-mediated m6A modification within microglia activates the TRAF6/ECSIT signaling pathway, induces mitochondrial oxidative stress in PVN neurons, and stimulates sympathetic hyperactivity, thereby contributing to the development of post-MI ventricular arrhythmias." (PMID 41294833, 2025). "For instance, METTL3 affected the processing and maturation of let-7e and miR-17-92 clusters to promote the formation of restorative neovascularization around myocardial infarction, thus improving cardiac function, suggesting that METTL3 was a favorable factor in myocardial infarction." (PMID 39893158, 2025). "Therefore, METTL3 can serve as an anti-inflammatory target during myocardial infarction to reduce tissue damage." (PMID 40005339, 2025). "Whether METTL3 regulates the occurrence and development of myocardial infarction through the m6A modification of TNC mRNA deserves our study." (PMID 36980863, 2023). "Furthermore, METTL3 participated in sympathetic neural remodeling post-myocardial infarction (MI) via the NF-κB pathway and reactive oxygen species (ROS) production." (PMID 36246528, 2022).
myocardial infarction (continued). "In contrast, knock out of methyltransferase-like 3 (METTL3), a N6-methyladenosine writer, whose expression levels raise postnatally, induces cardiomyocyte cell cycle re-entry, reduces scar size and boosts cardiac function after myocardial infarction, by regulating the miR-143-YAP axis." (PMID 34692797, 2021). "METTL3 expression is significantly elevated in ischaemic cardiac tissues, and inhibition of METTL3 ameliorates myocardial fibrosis induced by myocardial infarction (MI)." (PMID 41194259, 2025). "Following induction of myocardial infarction, we observed decreased protein expression of LC3B-II/LC3B-I and ATG7, alongside increased expression of p62, in cardiac tissues of METTL3-overexpressing mice compared to controls, indicating suppressed autophagy levels." (PMID 39893158, 2025). "However, although the authors reported that Mettl3 knockout mice had no abnormalities in cardiac structure or function under normal conditions, they did not evaluate cardiac changes after myocardial infarction or I/R injury in vivo." (PMID 34221238, 2021).
Alzheimer disease (19 papers, 2020 to 2025). A progressive, neurodegenerative disease characterized by loss of function and death of nerve cells in several areas of the brain leading to loss of cognitive function such as memory and language. "This study reveals that loss of METTL3, and the corresponding changes in m6A modifications, leads to enhanced brain infiltration of monocyte-derived macrophages in a mouse model of Alzheimer’s Disease, promoting Aβ clearance and ameliorating pathology and cognitive decline." (PMID 36881554, 2023). "Of note, a prior article illustrated that METTL3 mRNA was declined in the hippocampal tissue of postmortem patients with Alzheimer's disease, which corroborated our findings of METTL3 downregulation in MPTP‐induced PD mice." (PMID 37735974, 2024). "Accumulating researches demonstrated METTL3 plays a crucial role in the pathogenesis of neurodegenerative diseases, such as Alzheimer's disease and Parkinson's disease." (PMID 36977205, 2023). "For example, accumulation of methyltransferase-like 3 (Mettl3) is identified in the insoluble fractions of the postmortem brain samples of patients with Alzheimer's disease, which is positively correlated with the examined levels of insoluble Tau protein." (PMID 37737187, 2023). "METTL3 reduction can also result in m6A dysregulation leading to neurodegeneration in Alzheimer's disease." (PMID 35186167, 2022). "A recent study showed that m6A mRNA and METTL3 expression were elevated in the cortex of Alzheimer disease model mouse." (PMID 33869171, 2021). "It has been reported that KDM1A-mediated upregulation of METTL3 ameliorates Alzheimer's disease." (PMID 39800682, 2025). "Of note, METTL3 is downregulated in human Alzheimer's disease brain." (PMID 37735974, 2024). "METTL3 silencing results in neuronal death in Alzheimer's disease in vivo and in vitro." (PMID 37735974, 2024). "(2020) confirmed aberrant METTL3 levels in the hippocampus of the Alzheimer's disease patients brain induced an epitranscriptomic mechanism, which resulted in the changes in related gene expression patterns in Alzheimer's disease." (PMID 36977205, 2023). "In humans, patients with decreased expression levels of both METTL3 and NDUFA10 are more likely to develop Alzheimer’s disease." (PMID 39344412, 2024).
renal fibrosis (19 papers, 2020 to 2026). A final common manifestation of a wide variety of chronic kidney diseases characterized by glomerulosclerosis and tubulointerstitial fibrosis. "Gene silencing and overexpression combined with RNA immunoprecipitation were performed to investigate the underlying mechanism by which METTL3 regulates the Ena/VASP‐like (EVL) m6A modification that promotes renal fibrosis." (PMID 37537731, 2023). "Therefore, the Mettl3/Pfkfb3/lactate/H3K18la/PD-L1 pathway was a common mechanism underlying the development of both renal fibrosis and tumor growth during repeated low-dose CDDP-based cancer therapy." (PMID 40765834, 2025). "In summary, our study highlights Mettl3's role in CDDP-induced renal fibrosis, explains the underlying molecular mechanisms, and provides evidence that Mettl3 methyltransferase inhibition can both alleviate low-dose CDDP-induced renal fibrosis and enhance CDDP's tumor-killing efficiency." (PMID 40765834, 2025). "Functionally, we disclose that the knockout of Mettl3 in proximal tubules mitigates repeated low-dose CDDP-induced renal fibrosis both in vitro and in vivo." (PMID 40765834, 2025). "m6A RNA methylation was found to be significantly elevated in renal fibrosis, accompanied by increased expression of key m6A regulators, including METTL3, METTL14, ALKBH5, YTHDF1, and YTHDF3." (PMID 39756462, 2025). "To validate the results obtained from the mouse CAR model, we applied clinical biopsy specimens from patients with CAR to assess the presence of MMT cells (co‐expressing CD68 and α‐SMA) and the METTL3 expression across different extents of renal fibrosis." (PMID 39869489, 2025). "The data show that Pfkfb3, downstream gene of Mettl3, promotes the progression of renal fibrosis as well as production of production of pyruvate and lactate during repeated low-dose CDDP." (PMID 40765834, 2025). "Our study provides evidence from cellular, animal, and human models, demonstrating that increased m6A modification and METTL3 expression are strongly associated with enhanced MMT and renal fibrosis during CAR." (PMID 39869489, 2025). "In the current study, we discovered that Mettl3 increases the stability of Pfkfb3 via m6A modification to induce the development of renal fibrosis." (PMID 40765834, 2025). "Given that METTL3 serves as a key component of m6A modification and its remarkable increase in the MMT cells, we next focused on METTL3 to explore the mechanism behind the increased m6A modification with renal fibrosis." (PMID 39869489, 2025). "METTL3, a key enzyme in N6‐methyladenosine (m6A) modification, plays a crucial role in the progression of renal fibrosis, particularly in chronic active renal allograft rejection (CAR)." (PMID 39869489, 2025). "We found that METTL3 was consistently induced in murine models of HN and uric acid‐treated renal tubular epithelial cells (TECs), which show an obvious correlation with renal fibrosis and injury." (PMID 40100069, 2025). "We found that treatment with STM2457 or with AAV9‐mediated METTL3 silencing protected against renal fibrosis and inflammation." (PMID 40100069, 2025). "We also confirmed the importance of METTL3 in renal fibrosis by using AAV9‐mediated METTL3 silencing mice with hyperuricemia or a specific METTL3 inhibitor STM2457." (PMID 40100069, 2025). "Collectively, our data suggests that low-dose CDDP induces renal fibrosis and upregulates Mettl3 expression." (PMID 40765834, 2025). "For instance, METTL3-catalyzed m6A modification promotes renal fibrosis by promoting miR-21-5p maturation." (PMID 37815911, 2024). "After defining the role and mechanism of METTL3‐dominated m6A modification of EVL mRNA in renal fibrosis, we investigated the function and possible mechanism of EVL." (PMID 37537731, 2023).
renal fibrosis (continued). "Molecular docking and virtual screening based on the structure of METTL3 identified a TCM monomer named isoforsythiaside, which inhibited METTL3 activity together with the METTL3/EVL m6A axis to exert anti‐renal fibrosis effects." (PMID 37537731, 2023). "After clarifying the importance of METTL3 in the mouse renal fibrosis models induced by UUO and I/R, we also assessed the function of METTL3 in TGF‐β1 (5 ng/mL)‐ and H/R (9/3 h, three cycles)‐induced fibrotic responses in HK‐2 cells." (PMID 37537731, 2023). "Collectively, the overactivated METTL3/EVL m6A axis is a potential target for renal fibrosis therapy, and the pharmacological inhibition of METTL3 activity by isoforsythiaside suggests that it is a promising anti‐renal fibrosis agent." (PMID 37537731, 2023). "Initially, we emphasised the characteristics and potential functions of METTL3 and m6A modifications in renal fibrosis." (PMID 37537731, 2023). "Based on these findings, EVL is a potential target gene for METTL3‐mediated m6A modifications during renal fibrosis." (PMID 37537731, 2023). "During the mechanistic exploration phase, we investigated the elaborated molecular mechanisms of METTL3 in promoting renal fibrosis." (PMID 37537731, 2023). "Collectively, these results suggest that EVL is an important direct target gene for METTL3‐mediated m6A modifications during renal fibrosis." (PMID 37537731, 2023). "In the present study, we revealed compelling evidence linking upregulated METTL3 and overactivated m6A modifications closely to renal fibrosis." (PMID 37537731, 2023). "Together, the present findings provide insight into the function and mechanism of METTL3‐mediated EVL m6A modifications in renal fibrosis and comprehensively expand the understanding of related studies." (PMID 37537731, 2023). "Dysregulation of m6A regulators, including the upregulation of METTL3 and the downregulation of YTHDF2, has been linked to the activation of TGF-β signaling pathways and the subsequent development of renal fibrosis in CKD." (PMID 37841018, 2023). "To explore the specific characteristics of m6A modifications that regulate mRNA in renal fibrosis and identify potential targets for METTL3, we performed m6A‐Seq and RNA‐Seq on the kidneys of UUO mice." (PMID 37537731, 2023). "After a comprehensive screening, we identified and validated a novel TCM monomer inhibitor of METTL3 at the pharmacological level and evaluated its effectiveness in treating renal fibrosis in mice." (PMID 37537731, 2023). "In the present study, we generated obstructive renal fibrosis models in mice and enhanced or inhibited the expression of miR‐21‐5p, METTL3, HNRNPA2B1 and ERK in HK‐2 cells through transfection or chemical inhibition." (PMID 34164910, 2021). "Based on the literature, we hypothesize that Mettl3 inhibition could reduce CDDP-induced renal fibrosis and improve CDDP efficacy." (PMID 40765834, 2025). "Mettl3 is a promising target for managing renal fibrosis during cisplatin therapy." (PMID 40765834, 2025). "Collectively, targeting Mettl3 might offer an effective therapeutic strategy during cisplatin-based chemotherapy-induced renal fibrosis, and PLGA-encapsulated Levosimendan is a potential intervention approach." (PMID 40765834, 2025). "Furthermore, antisense oligonucleotides targeting METTL3 expression have demonstrated potential for alleviating renal fibrosis." (PMID 39869489, 2025). "Additionally, METTL3‐mediated methylation of MALAT1 m6A exacerbates renal fibrosis in obstructive nephropathy." (PMID 40100069, 2025). "Targeting Mettl3 might provide a novel therapeutic strategy to prevent renal fibrosis during cisplatin-based chemotherapy, and PLGA-encapsulated Levosimendan represents a promising therapeutic approach." (PMID 40765834, 2025).